ST6GAL1 (ST6 beta-galactoside alpha-2,6-sialyltransferase 1)
Diseases named in the same sentence as ST6GAL1 in open-access papers (continued):
Sharing a sentence is not in itself a finding about the gene and the disease.
tumor (continued). "Thus, the differential distribution of ST6GAL1 membrane-bound form in sEVs according to tumor aggressiveness suggests its potential as a biomarker of progression in PrCa." (PMID 40938891, 2025). "As ST6GAL1 is the predominant enzyme responsible for adding α-2,6-linkages of sialic acid to N-glycosylated proteins, we measured total sialylation levels and observed increased sialylation in tumor samples, mirroring the elevated ST6GAL1 protein expression." (PMID 39937175, 2025). "Interestingly, some investigations showed that hyper-sialylation of some membrane receptors, due to ST6GAL1 overexpression, correlated with the ability of tumor cells to migrate and metastasize." (PMID 41226744, 2025). "Furthermore, multiple studies have demonstrated that ST6GAL1 expression correlates with higher tumor grade, metastasis, and poor prognosis." (PMID 39937175, 2025). "Moreover, ST6GAL1 knockdown help improve tumor response together with anti‐PD‐L1 therapy in vivo, implicating that ST6GAL1 has the potential to be a vital target in improving drug resistance in immunotherapy." (PMID 40847469, 2025). "Additionally, HE and IHC analyses revealed higher ST6GAL1 expression in tumor regions compared to adjacent normal tissue." (PMID 39937175, 2025). "Notably, the combination of ST6GAL1 knockdown and anti–PD‐L1 therapy elicited the most pronounced anti‐tumor response, indicating a potential synergistic effect." (PMID 40847469, 2025). "Several of the GRGs and GRPs commonly correlated with survival in different tumor types are actually associated with specific cells in the stromal compartment (as MFNG in all immune cells, LGALS2 in myeloid cells, ST6GAL1 in B and plasma cells and CHPF and ST3GAL4 for fibroblasts)." (PMID 38384845, 2024). "To investigate if prostate-derived tumours growing in bone also have high levels of ST6GAL1 we analysed 20 rapid autopsy samples taken from men with bone metastasis (these samples were from prostate-derived tumours growing in bone and were obtained within hours of death)." (PMID 38772281, 2024). "The current finding that ST6GAL1 expression is induced by IL-1β and IL-6 suggests that the inflammatory milieu associated with PDAC may act in concert with tumor-intrinsic mechanisms to promote high levels of ST6GAL1 expression." (PMID 39260693, 2024). "Interestingly, ST6GAL1 has been shown to protect tumor cells from hypoxic stress by increasing the expression of hypoxia-inducible factor alpha (HIF-1α)." (PMID 38067186, 2023). "Tumor growth and differential ST6GAL1 expression in tumors were verified by histology." (PMID 37643018, 2023). "In the aggregate, these data suggest that ST6GAL1 may contribute to neoplasia by inducing acinar cells to adopt progenitor-like characteristics." (PMID 37643018, 2023). "Notably, endogenous ST6GAL1 was expressed in the PanIN lesions of KC mice (arrow), illustrating an upregulation of ST6GAL1 in early stages of neoplasia." (PMID 37643018, 2023). "ST6Gal1 is also detected in the tumor vessels and regulates tumor angiogenesis through PECAM–VEGFR2 complex signaling, which is also indirectly associated with tumor progression or regression." (PMID 36622466, 2023). "Our finding indicated that there existed a TINCR/miR-195-3p/ST6GAL1/NF-κB signaling regulatory axis that regulated tumor progression and oxaliplatin resistance, which might be exploited for anticancer therapy in HCC." (PMID 34980201, 2022). "The study also suggested that tumor cells with a higher level of endogenous ST6GAL1 protein released exosomes can transfer ST6GAL1 into the lower natively expressing ST6GAL1 tumor cells and enhance ST6GAL1-mediated cellular signaling in the recipient cells." (PMID 35676533, 2022). "This study provides a novel mechanism by which ST6GAL1 may promote tumor cell survival within TNF-rich inflammatory tumor microenvironments." (PMID 33921986, 2021).
tumor (continued). "Interestingly, ST6Gal1 was shown to protect tumor cells from hypoxic stress, eventually by enhancing the expression of hypoxia-inducible factor-1α (HIF-1α)." (PMID 34975914, 2021). "Furthermore, ST6GAL1 induced expression of two key tumor-promoting transcription factors, SOX9 and Slug, also known to play crucial roles in the maintenance of stem/progenitor pools." (PMID 33921986, 2021). "In addition, ST6GAL1 has been recently proposed as a novel tumor-derived secreted biomarker that identifies lenvatinib-susceptible FGF19-driven highly malignant HCCs." (PMID 33921986, 2021). "In addition, an α2‐6 sialylation and the expression of St6gal1 were upregulated during epithelial to mesenchymal transition and tumor formation." (PMID 32681764, 2020). "ST6GAL1 could induce anti-apoptosis and drug resistance to help tumor cells escape from the influence of chemotherapeutic drugs." (PMID 31096997, 2019). "The levels of ST6GAL1 and Ki67 in xenograft tumor were also verified by IHC staining." (PMID 31096997, 2019). "Additionally, ST6GAL1 was reported to protect tumor cells against hypoxia by enhancing HIF-1α signaling." (PMID 30478534, 2019). "SW480 cells transfected with ST6GAL1 showed larger tumor volume compared with the control group." (PMID 31694696, 2019). "Established xenograft model showed decreased level of ST6GAL1 inhibited tumor growth." (PMID 31096997, 2019). "We postulate that some of the tumor-promoting activity of the 3q26 amplicon may be mediated by ST6GAL1." (PMID 31610800, 2019). "Moreover, the high occupancy of the bone marrow by the neoplasm, which in some cases approached 60%, allowed for an assessment of the consequences of pathologically elevated ST6GAL1 within the bone marrow microenvironment." (PMID 31408003, 2019). "Tumor tissues expressed higher levels of ST6Gal1 than their normal adjacent tissues." (PMID 28032597, 2017). "Epigenetic inactivation of ST6GAL1 is indicated a tumor suppressive role in bladder carcinogenesis." (PMID 25774687, 2015). "Tumor-specific DNA methylation of the ST6GAL1 promoter region was frequently found in pT2-4 tumors (53.6% (22/41)), whereas only 13.8% (4/29) of pTa tumors showed ST6GAL1 promoter methylation." (PMID 25465919, 2014). "Only one patient showed an increase with a FC >2 in ST6GAL1 gene expression and two patients an insignificant change, not impairing a pronounced loss of ST6GAL1 in invasive tumor stages." (PMID 25465919, 2014). "Similarly, tumor growth curves revealed that ST6GAL1 knockdown significantly suppressed tumor progression under anti‐PD‐L1 treatment, whereas ST6GAL1 overexpression slightly dampened this synergistic effect, although the differences were not statistically significant." (PMID 40847469, 2025). "Similarly, ST6GAL1 protein expression was elevated in tumor samples." (PMID 39937175, 2025). "Finally, we measured the levels of St3Gal1, St6Gal1, and St6GalNac3 in the tumor explants." (PMID 39104719, 2024). "Interestingly, ST6GAL1 was confirmed extremely higher in CRC tumor tissues." (PMID 31694696, 2019). "ST6GAL1 knockdown in MC38 tumor‐bearing mice enhances the antitumor effect of anti‐PD‐L1 therapy, resulting in smaller tumor sizes and reduced tumor volume compared to control groups." (PMID 40847469, 2025). "To further study the role of ST6GAL1 in vivo, we established a subcutaneous tumor implantation model in C57BL/6 mice using MC38 cells transfected with NC, ST6GAL1‐KD, or ST6GAL1‐OE lentivirus." (PMID 40847469, 2025). "Through in silico analysis we showed that mRNAs of only ST6GAL1, ST3GAL2 and ST8SIA4 are significantly upregulated in GBM tissues compared to non-tumor ones." (PMID 41226744, 2025). "In the current study, we evaluated the regulation of ST6GAL1 by two pro-inflammatory cytokines, IL-1β and IL-6, which are abundant within the PDAC tumor microenvironment." (PMID 39260693, 2024).
tumor (continued). "In contrast, robust ST6GAL1 expression is observed in PDAC cells, and ST6GAL1 levels progressively increase as the tumor evolves from early to late stage." (PMID 39260693, 2024). "We postulate that the ST6GAL1-mediated α2-6 sialylation of TNFR1 and Fas functions as a critical mechanism enabling tumor cell survival within the tumor microenvironment." (PMID 39615678, 2024). "As ST6GAL1 imparts progenitor-like characteristics, we interrogated ST6GAL1’s role in acinar to ductal metaplasia (ADM), a process that fosters neoplasia by reprogramming acinar cells into ductal, progenitor-like cells." (PMID 37643018, 2023). "As such, the depletion of ST6Gal1 led to decreased CD133+/ALDH1+ colon CSCs and an impaired tumor-initiating potential in PDAC MiaPaCa2 cells, as determined by in vivo limiting dilution assays." (PMID 37298124, 2023). "ST6GAL1 is upregulated in PDAC patient tissues and promotes PDAC progression in tumor xenograft models." (PMID 37643018, 2023). "We first verified ST6GAL1 overexpression in PDAC patient tissues, then established a tumor driver function for ST6GAL1 using tumor xenograft models and GEM models with dual expression of ST6GAL1 and oncogenic KRAS (KRASG12D)." (PMID 37643018, 2023). "Several glycosyltransferases, including MGAT5, FUT8, ST6GAL1, ST6GALNAC1 and ST8SIA1 have an established reputation as tumor-promoting enzymes." (PMID 35565254, 2022). "The interplay between the different sialyltransferases known to add NeuAc residues onto N-glycans, such as ST6GAL1 or the ST3GAL4/5/6, clearly plays a major role in this context of the tumour microenvironment." (PMID 36289103, 2022). "While downregulation of ST6Gal1 transcription was shown to stimulate tumor cell proliferation both in vitro and in vivo, NDAT demonstrated its capability to reduce ST6Gal1 expression and CRC growth." (PMID 34359854, 2021). "Using complementary assays, authors demonstrated that ST6GAL1 confers CSC characteristics, including spheroid growth, chemotherapy resistance, and tumor-initiating potential." (PMID 33921986, 2021). "Consistently, intracranial injection of U373 MG glioma cells overexpressing ST6GAL1 or ST3GAL3 led, respectively, to a complete lack or drastic reduction in tumor growth in vivo." (PMID 33921986, 2021). "While downregulation of ST6Gal1 transcription has been shown to stimulate tumor cell proliferation both in vitro and in vivo, NDAT demonstrated its capability to decrease ST6Gal1 expression and CRC growth." (PMID 33827580, 2021). "Each individual tumor specimen is represented by a single bar, with red bars indicating patients with CNGs in SOX2 or ST6GAL1." (PMID 31610800, 2019). "In cervical neoplasia, an increased expression of the sialyltransferase genes ST6GAL1 and ST3GAL3 has been reported as well as increased sialic acid and the tumour antigens sLe(X), Tn and sTn." (PMID 30038662, 2018). "Demethylation application led to an upregulation of ST6GAL1 mRNA expression approximately by 18,000 fold in highly methylated RT112 tumor cells." (PMID 25465919, 2014). "To confirm this hypothesis, we established a subcutaneous tumor implantation model using C57BL/6 mice with ST6GAL1‐NC, ST6GAL1‐KD, and ST6GAL1‐OE MC38 cell lines, followed by treatment with either PBS or a combination of anti‐PD‐L1 and cisplatin." (PMID 40847469, 2025). "Additionally, tumor adhesion and metastasis-promoting molecules, including ITGB4 and ITGB8, whereas ITGA1 and ITGA2 were downregulated in ST6GAL1-knockdown cells." (PMID 39937175, 2025). "Moreover, ST6GAL1 overexpression increased the migration of SW48 cells, further highlighting the role of LGALS3BP sialylation in regulating tumor cell migration." (PMID 39937175, 2025). "Knockout ST6GAL1, lacking the α2,6-sialylation enzyme, is shown to exhibit impaired tumor angiogenesis through enhanced endothelial apoptosis." (PMID 39290304, 2024).
tumor (continued). "Numbers of CD206+ M2 macrophages are increased in castrate resistant disease, 88, 89 and consistent with our findings for ST6GAL1, a recent study showed CD206+ M2 macrophages are upregulated in bone metastatic CRPC specimens compared with primary tumours or lymph node metastases." (PMID 38772281, 2024). "We did not detect a significant difference in ST6GAL1 expression between Gleason 7–8 and Gleason 8–10 tumours in this TMA (unpaired t test, p = 0.4542)." (PMID 38772281, 2024). "In particular, tumor cells often display elevated surface sialylation as a consequence of increased expression of various Golgi sialyltransferases, including ST6 β-galactoside α2,6 sialyltransferase 1 (ST6GAL1)." (PMID 37643018, 2023). "Our studies support this concept, and furthermore indicate that ST6Gal1 in BCP-ALL is neither an oncogene nor a tumor suppressor." (PMID 35371997, 2022). "The impact of this non-canonical extrinsic mechanism of ST6GAL1 on tumor cell pathobiology is not known." (PMID 35676533, 2022). "In addition to direct roles in neoplastic cells, ST6Gal1 and TGF-β signaling interactions can impact the tumor microenvironment." (PMID 36106023, 2022). "When ST6Gal1 knockout mice were injected with lung carcinoma cells, there was reduced PECAM surface stabilization and the PECAM-VEGFR2 interaction was compromised: this led to apoptosis in endothelial cells and inhibition of tumor angiogenesis." (PMID 36106023, 2022). "The down-regulation of ST6GAL1 has been shown to interfere with the transduction of PECAM-VEGFR2 and integrin-β3 in mouse Lewis lung carcinoma cells, leading to endothelial cell apoptosis, which impairs tumor angiogenesis." (PMID 33921986, 2021). "Initial analysis of a mixed-stage tumor cohort failed to reveal a clear pattern of up- or downregulation in ST6GAL1 expression." (PMID 25465919, 2014). "Furthermore, ST6GAL1 upregulation in ovarian and pancreatic carcinomas induces the expression of SRY-box transcription factor 9 (SOX-9) and Snail family transcriptional repressor 2 (SNAI2), both key tumor-promoting transcription factors." (PMID 39937175, 2025). "In addition, the sialyltransferase ST6GAL1 regulated the abnormal glycosylation of some tumour suppressor genes to promote tumourigenesis, suggesting that COG complex acts as upstream regulators of these genes to regulate their function in tumours." (PMID 34539936, 2021). "Furthermore, lectin blot analysis revealed a significant reduction in SNA binding signals following ST6GAL1 knockdown, while MAL‐I binding remained unchanged, suggesting that ST6GAL1 specifically regulates tumor progression predominantly via α2,6‐sialylation without affecting α2,3‐sialylation." (PMID 40847469, 2025). "Enforcing ST6GAL1 in CAR-T cells did not weaken tumoricidal activity and significantly improved anti-tumor responses and in vivo persistence." (PMID 41789075, 2026). "Reflecting the variance seen in our tumor population, the RT4 papillary-invasive cell line showed no ST6GAL1 promoter methylation." (PMID 25465919, 2014).
infection (17 papers, 2014 to 2025). The state of being infected such as from the introduction of a foreign agent such as serum, vaccine, antigenic substance or organism. "Similarly, at day 7 PI, infection caused a significant decrease of St3Gal4, while St6GalNAc1, St6Gal1, and St3Gal1 showed a trend toward reduction." (PMID 39412866, 2024). "However, only the infection with G9P was associated with a significant downregulation of the expression of genes encoding ST3Gal (ST3Gal2, ST3Gal3, and ST3Gal6) and ST6Gal (ST6Gal1) sialyltransferases." (PMID 37515094, 2023). "In accordance, infection levels similar or even higher as observed in HEKWT or HEKN cells were obtained in HEKΔSiaN cells transfected with ST3Gal4 or ST6Gal1." (PMID 40487452, 2025). "In contrast, WU95Hu−H3 infection of ST3Gal4-transfected cells was relatively low in comparison to binding but relatively efficient in ST6Gal1-transfected cells." (PMID 40487452, 2025). "On the other hand, sialylation of O-glycans or GSLs by ST6Gal1 supported infection of all human strains to 35% to 100% of wild-type levels." (PMID 40487452, 2025). "Receptor binding specificity was compared to receptor-specific infection efficiency by plotting, for both, the 2-3Sia/2-6Sia ratio derived from ST3Gal4-and ST6Gal1-transfected HEKΔSiaN, HEKΔSiaO, HEKΔSiaGSL, and HEKΔSia cells." (PMID 40487452, 2025). "Remarkably, a maximal infection efficiency was reached for 2-6Sia-dependent entry, followed by a decline upon further increase of transfected ST6Gal1 dose." (PMID 35831293, 2022). "In a previous report, Nasirikenari and colleagues demonstrated that administration of ST6GAL1 reduced infection in a mouse model of acute lung inflammation, while transient depression of circulating ST6GAL1 accompanied acute airway inflammation." (PMID 34290711, 2021). "In this study, we show that a recombinant protein corresponding to the soluble form of ST6Gal-1 (rST6G) was effective in mitigating infection-driven acute inflammation." (PMID 30778346, 2019). "We further posit that infusion of pure, recombinant ST6Gal-1 (rST6G), resulting only in temporary elevation of blood ST6Gal-1 activity can be effective against infection-driven inflammation." (PMID 30778346, 2019). "Here, we posit that an infection-driven acute inflammation can also be attenuated by raising circulatory ST6Gal-1." (PMID 30778346, 2019). "Circulatory ST6Gal-1 levels respond to inflammation, infection, and malignancy in mammals, including humans." (PMID 30294329, 2018). "Comparison of infection into transiently transfected HEKΔSia cells with stable knock-ins of ST6Gal1 or ST3Gal4 in HEKΔSia cells validated the use of the cell-based glycan array as specificity and efficiency of infection by strains WU95Hu−H3 and HU02Av−H5 was similar in both cases." (PMID 40487452, 2025). "Here, we compared virus binding to ST3Gal4- or ST6Gal1-transfected cells with infection." (PMID 40487452, 2025). "Additionally, we identified 10 genomic regions associated with breakthrough infection (SLC6A20, ST6GAL1, MUC16, FUT6, MXI1, MUC4, HMGN2P18-KRTCAP2, NFKBIZ and APOC1), and one with breakthrough severity (APOE)." (PMID 39384777, 2024). "Similarly, an ST6Gal1 concentration-dependent increase of infection by 2-3Sia specific strains HU02 and PR8 was observed in combination with the highest concentration of ST3Gal4 (0.2 ng)." (PMID 35831293, 2022). "In the current report, we show that an infection-driven inflammation can also be controlled effectively by direct intravenous infusion of pure recombinant ST6Gal-1 protein, despite using a primitive rST6G formulation that is very rapidly cleared from the blood." (PMID 30778346, 2019). "Compared to control cells, all KO cell lines (ST3GAL4, SLC31A1, ST6GAL1, and ST3GAL4/ST6GAL1DKO) showed significantly reduced PEDV infection." (PMID 40767522, 2025).
infection (continued). "An ST3Gal4 concentration-dependent increase of infection by 2-6Sia specific strains BK79 and WU95 was observed in combination with the highest concentration of ST6Gal1 (0.8 ng)." (PMID 35831293, 2022). "The highest expression level of STs in human respiratory tissues are ST6GAL1 and ST3GAL4, which are closely related to the infection of influenza viruses (41, –, 43)." (PMID 35044216, 2022). "Compared to WT cells, infection of these viruses was significantly reduced in cells lacking ST3GAL4 and ST6GAL1." (PMID 40767522, 2025).
adenocarcinoma (3 papers, 2019 to 2023). A common cancer characterized by the presence of malignant glandular cells. "ST6GAL1 promotes PanIN formation, adenocarcinoma, and metastasis." (PMID 37643018, 2023).